GDNF (glial cell derived neurotrophic factor)
Diseases named in the same sentence as GDNF in open-access papers (continued):
Sharing a sentence is not in itself a finding about the gene and the disease.
memory impairment (8 papers, 2016 to 2024). "Furthermore, they may prevent memory impairment by regulating the expression of neurotrophic factors such as glial cell line-derived neurotrophic factor (GDNF) and brain-derived neurotrophic factor (BDNF)." (PMID 38612870, 2024). "In conclusion, this study suggests that KIT may ameliorate a stress-induced depressed state and memory impairment via prevention of adverse effects of stress on hippocampal cell survival, the number of new-born hippocampal immature neurons, accumbal dendritic spines and accumbal GDNF levels." (PMID 34765515, 2021). "Also, sodium butyrate treatment re-established brain-derived neurotrophic factor (BDNF) and glial cell line-derived neurotrophic factor (GDNF) expression, preventing memory impairment in experimental pneumococcal meningitis." (PMID 35606817, 2022). "Despite the absence of pronounced memory impairments in the late post-hypoxic period, it is important to note that animals with increased expression of both BDNF and GDNF lacked the strategy of chaotic search in the Morris maze, which indicates an improvement in cognitive and mnestic functions." (PMID 36077134, 2022).
brain injury (7 papers, 2009 to 2024). Acute and chronic (see also brain INJURIES, CHRONIC) injuries to the brain, including the cerebral hemispheres, CEREBELLUM, and brain STEM. "The release of GDNF is expected to have therapeutic potential for neurodegenerative diseases, traumatic and inflammatory brain injuries." (PMID 36055989, 2022). "GDNF with its trophic effects on neurons has been shown to have neuroprotective effects after ischemic brain injury." (PMID 35806000, 2022). "GDNF has also been shown to have neuroprotective effects following ischemic brain injury when introduced to the brain by viral vectors or GDNF-expressing cells." (PMID 25942688, 2015). "In a model of traumatic brain injury, HBOT promoted the expression of neurotrophic factors such as NGF, brain-derived neurotrophic factor (BDNF), glial cell line-derived neurotrophic factor (GDNF), and neurotrophin-3 (NT-3) in vivo." (PMID 38396709, 2024). "This process is mediated by a neurotrophic factor, glial cell-derived neurotrophic factor (GDNF), which is involved in neural plasticity, particularly in brain trauma and cognitive and memory impairment." (PMID 35360515, 2022).
Infertility (7 papers, 2016 to 2025). "Research emphasizes its importance in endometriosis, infertility, and its influence on other genes like GDNF, impacting progesterone availability, a known factor in breakthrough bleeding." (PMID 38745005, 2024). "This resemblance prompted us to ask if GDNF expression is abnormally low in these infertile human testes." (PMID 35721702, 2022). "We also found that excess GDNF can result in infertility in adults likely due to defects in common nephric duct remodeling, a developmental process necessary for segregation of ureters from reproductive organs and known to depend on GDNF receptor RET12,17,18." (PMID 30923332, 2019). "Spermatogenesis in heterozygous GDNF knockout mice gradually disappears and leads to infertility." (PMID 27769051, 2016). "A shifted balance in favor of GDNF expression, as seen in our results, might thus inhibit SSC differentiation and lead to infertility." (PMID 39940876, 2025).
psychosis (7 papers, 2022 to 2025). "The cross-sectional nature of our data poses a limitation in establishing causal relationships between GDNF or miRNA levels and the functioning in individuals with first-episode psychosis." (PMID 38645418, 2024). "Given the potential neuroprotective role of GDNF and its association with cognitive functioning in individuals with first-episode psychosis, further research is warranted to elucidate the underlying mechanisms of its effects on neuronal plasticity and cognitive performance." (PMID 38645418, 2024). "Importantly, our study is the first to establish a positive association between peripheral blood GDNF concentrations and cognitive enhancement observed over the three-month treatment period in individuals experiencing their first episode of psychosis." (PMID 38645418, 2024). "We have not only shown that peripheral blood GDNF concentrations are closely linked to cognitive functions in individuals experiencing their first episode of psychosis but also made the pioneering discovery that child abuse is associated with reduced GDNF levels in these patients." (PMID 38645418, 2024). "Overall, the study highlights the importance of understanding the mechanisms linking childhood trauma and psychosis, and the potential role of GDNF in this process." (PMID 38645418, 2024). "The findings of the present study showed that peripheral blood GDNF concentrations are closely related to cognitive functioning in individuals with first-episode psychosis." (PMID 38645418, 2024). "BDNF and GDNF, the most extensively investigated neurotrophins related to psychotic disorders, play a key role in cognitive processes." (PMID 39886050, 2024). "The assessment of GDNF and miR-29a-3p levels presents a promising approach for evaluating cognitive status in individuals with psychosis." (PMID 38645418, 2024). "This is important, as the observed dual effect suggests a mechanism as to how methamphetamine induces psychosis with incomplete penetrance—individuals with higher GDNF induction and less prominent GFRa1/RET downregulation are more likely to develop psychosis." (PMID 37759827, 2023). "Overall, our study results indicate that the evaluation of GDNF and miR-29a-3p levels may be a promising approach for assessing cognitive status in patients with psychosis." (PMID 38645418, 2024). "Our research findings suggest that child abuse may induce changes in GDNF expression among patients with psychosis." (PMID 38645418, 2024). "Our results suggest a potential mechanism as to how methamphetamine elicits individual psychosis risk in young adults—variation in initial striatal GDNF induction and subsequent GFRα1 and RET downregulation may determine individual susceptibility to psychosis." (PMID 37759827, 2023). "Our results may guide future experiments and precision medicine development for methamphetamine-induced psychosis using GDNF/GFRa1/RET antagonists." (PMID 37759827, 2023). "In that regard, first episode psychosis patients with high levels of GDNF in the CSF may be of special interest for future research on A2AR and RET inhibition therapy." (PMID 35618883, 2022). "Furthermore, amphetamine and its derivatives increase nigrostriatal GDNF expression in experimental animals and trigger psychosis in some individuals." (PMID 35618883, 2022). "This, when supported by further analysis in methamphetamine-induced psychosis patients, suggests that temporary inhibition of GDNF signaling may serve as a future precision medicine for the treatment of methamphetamine-induced psychosis patients with elevated GDNF responses." (PMID 37759827, 2023).
brain tumors (6 papers, 1999 to 2025). "We investigated a panel of 36 independent cases of mainly advanced sporadic brain tumours for the presence of mutations in GDNF and GFRα-1." (PMID 10408842, 1999). "Testosterone contributes to brain tumor growth via GDNF and inflammation." (PMID 37833789, 2023). "Our data suggest that intragenic point mutations of GDNF or GFRα-1 are not a common aetiologic event in brain tumours." (PMID 10408842, 1999).
Constipation (6 papers, 2018 to 2024). Infrequent or difficult evacuation of feces. "Further, LP‐CQPC01‐FSM increased the mRNA and protein expression of Cu/Zn‐SOD, Mn‐SOD, CAT, c‐Kit, SCF, and GDNF and reduced the expression of TRPV1 and NOS relative to those of the mice with untreated constipation." (PMID 31289655, 2019). "The RT-PCR and immunohistochemical experiment showed that all three interventions relieved constipation by affecting aquaporins (AQP4 and AQP8), interstitial cells of Cajal (SCF and c-Kit), glial cell-derived neurotrophic factor (GDNF), and Nitric Oxide Synthase (NOS)." (PMID 36687730, 2022).
liver fibrosis (6 papers, 2020 to 2025). "We determined the diagnostic accuracy of serum GDNF in liver fibrosis and cirrhosis and compared that with other known markers." (PMID 35855954, 2022). "Further work is warranted to clarify the precise role of GDNF in the pathogenesis of liver fibrosis associated with NASH." (PMID 32175323, 2020). "However, in our previous preclinical study, we showed that GDNF level was associated with liver fibrosis developed in several different etiologies." (PMID 35855954, 2022). "GDNF is significantly upregulated in patients with advanced liver fibrosis and correlates with markers of HSC activation." (PMID 40260391, 2025). "In mice, GDNF overexpression exacerbated liver fibrosis, while silencing GDNF or blocking its signaling reduced fibrosis and HSC activation." (PMID 40260391, 2025). "In particular, glial cell line‐derived neurotrophic factor (GDNF) involved in TGF‐β/Smad signalling is critical in regulation of liver fibrosis." (PMID 38520214, 2024). "In pre-clinical models of hepatic fibrosis, GDNF has been found to have varied effects, inducing cirrhosis in CCL4 and bile duct ligation models but protecting against hepatic fibrosis in a high-fat-diet-fed model." (PMID 38339124, 2024). "Consistent with in vitro cytological results, our in vivo data showed that levels of miR‐125b and GDNF as well as markers of liver fibrosis underwent changes dependent on the expression of lncRNA CYTOR." (PMID 38520214, 2024). "Previous studies have identified GDNF as a potential predictive factor and important target for treatment of liver fibrosis." (PMID 38520214, 2024). "This study was performed on CCl4‐induced damaged liver cells and mouse liver fibrosis models with specific focus on regulation of the GDNF pathway by lncRNA CYTOR." (PMID 38520214, 2024). "Saffronin ameliorates liver fibrosis by inhibiting HSC activation via the lnc-LFAR1/MTF-1/GDNF axis." (PMID 37409114, 2023). "We recently reported that GDNF is the functional promoter of hepatic stellate cell activation and liver fibrosis mediated through ALK5/Smad signaling." (PMID 35855954, 2022). "GDNF's effects on liver fibrosis are contradictory by playing antifibrotic and profibrotic roles in different models." (PMID 32175323, 2020). "This pro-fibrotic role of GDNF in CCl4 and bile duct ligation models of hepatic fibrosis is opposite to what was seen in our study with HFD-fed model of NAFLD." (PMID 32175323, 2020). "Hepatic GDNF expression is elevated in patients with advanced liver fibrosis in conditions including NASH, alcoholic liver disease or hepatitis B virus infection." (PMID 32175323, 2020). "We further suggest that GDNF inhibition could be a therapeutic strategy for patients with liver fibrosis." (PMID 35855954, 2022). "We also found that hepatic GDNF levels were upregulated in human liver fibrosis." (PMID 35855954, 2022). "Whether the increase in GDNF plays a protective or exacerbating role in the pathogenesis of hepatic fibrosis remains elusive, and results are conflicting." (PMID 32175323, 2020). "Recently, we reported that GDNF promotes hepatic stellate cell activation and liver fibrosis via ALK5/Smad signaling in the preclinical mouse models of liver fibrosis." (PMID 35855954, 2022). "This exemplified the mechanism of GDNF-mediated liver fibrosis and implied that sGDNF might serve as a powerful noninvasive biomarker for diagnosing fibrosis and cirrhosis." (PMID 35855954, 2022). "Besides, we also showed that both by serum protein level and tissue mRNA expression in the liver, and GDNF was specifically correlated with liver fibrosis but not with the pattern of necrosis and the existence of steatosis." (PMID 35855954, 2022).
malignant melanoma (6 papers, 2010 to 2025). "Taken together with the finding of augmented proliferation of HM3KO cells after GDNF stimulation, our results suggest that GDNF-mediated c-RET kinase activation is associated with the pathogenesis of malignant melanoma." (PMID 20422010, 2010). "Furthermore, a previous report revealed that GDNF stimulation significantly amplified proliferation of human melanoma cells with polymorphism at G691S in c-RET." (PMID 20422010, 2010). "The expression levels of c-RET, GFRa1 and GDNF in G361 and SK-Mel28 human malignant melanoma cells were definitely lower or undetectably low compared with those in NHEM cells." (PMID 20422010, 2010). "Then we showed that transcript and protein of GFRa1, which is essential for c-RET/GDNF signaling, was expressed in malignant melanoma cells by real-time PCR and immunohistochemistry." (PMID 20422010, 2010). "We next examined the expression levels of c-RET, GFRa1 and GDNF in primary-cultured normal human epithelial melanocytes and human malignant melanoma cell lines (G361, SK-Mel28, MNT-1 and HM3KO)." (PMID 20422010, 2010). "We then showed that c-RET and GDNF transcript expression levels in human malignant melanoma cell lines (HM3KO and MNT-1) were higher than those in primary cultured normal human epithelial melanocytes (NHEM), while GFRa1 transcript expression levels were comparable among NHEM, HM3KO and MNT-1." (PMID 20422010, 2010). "Moreover, we for the first time demonstrated not only GFRa1 protein expression but also GDNF-mediated c-RET kinase activation via phosphorylated tyrosine 905 in human malignant melanoma cells." (PMID 20422010, 2010). "Our results showed that transcript expression levels of c-RET and GDNF in MNT-1 and HM3KO human malignant melanoma were definitely higher than those in NHEM cells, while GFRa1 expression levels were comparable in these cells." (PMID 20422010, 2010). "We finally examined the physiological effect of GDNF stimulation on proliferation of HM3KO and G361 human malignant melanoma cells, which have no polymorphism at the G691S juxtamembrane region in c-RET as shown in a previous study." (PMID 20422010, 2010). "In fact, not only GDNF-mediated c-RET kinase activation but also GFRa1 expression in human malignant melanoma cells has still not been elucidated." (PMID 20422010, 2010).
multiple sclerosis (6 papers, 2014 to 2025). A progressive autoimmune disorder affecting the central nervous system resulting in demyelination. "Our data demonstrate that the expression of GDNF is increased in astrocytes upon treatment with CSF from multiple sclerosis patients." (PMID 38564643, 2024). "Glial cell-derived neurotrophic factor (GDNF), insulin-like growth factor 1 and brain-derived neurotrophic factor are related to the nutritional support provided by oligodendrocytes for axons, which is predicted to be defective in multiple sclerosis." (PMID 34922574, 2021).
Tinnitus (6 papers, 2014 to 2023). Tinnitus is an auditory perception that can be described as the experience of sound, in the ear or in the head, in the absence of external acoustic stimulation. "Although underpowered, even if significance were achieved in the initial association study analyzing GDNF markers in German tinnitus patients, the replication study that followed studied the same three markers in a Turkish tinnitus group." (PMID 28533738, 2017). "However, the combination of BDNF and GDNF gene polymorphisms was more associated with the severity of tinnitus in women than in men." (PMID 34205595, 2021). "The top five proteins associated with tinnitus with a p value less than 0.02 were FGF-21, MCP4, GDNF, CXCL9, and MCP-1." (PMID 38079022, 2023). "In one study on GDNF and BDNF gene SNPs, there was no allelic association between two BDNF SNPs (rs6265, rs2049046) and three GDNF SNPs (rs1110149, rs884344, rs3812047) in patients with chronic subjective tinnitus." (PMID 34205595, 2021). "Genetics has been little explored in the context of tinnitus, with a few potential genes screened, including associated cardiovascular genes, neurotropic factors of BDNF and GDNF, potassium recycling pathway genes, GABAB receptor subunits, and serotonin receptor/transporters." (PMID 36556140, 2022).
colorectal cancer (5 papers, 2020 to 2024). A primary or metastatic malignant neoplasm that affects the colon or rectum. "NEAT1 is implicated in the regulation of cell proliferation and migration in colorectal cancer (CRC) through the NEAT1/miR-196a/GDNF pathway." (PMID 39830506, 2024). "Increased expression of GDNF enhances β1 integrin expression via signaling through RET/GFRα1 in colorectal cancer cell lines, thus strongly influencing adhesion to and invasion of the extracellular matrix (ECM)." (PMID 35582425, 2022). "Similarly, in colorectal cancer cell lines, β1 integrin expression is enhanced by increased GDNF expression via signaling through RET/GFRα1, notably influencing adhesion to and invasion of the ECM." (PMID 35582425, 2022). "Recent research in colorectal cancer (CRC) has indicated that miR-196a-5p exerts its function in cell proliferation and migration by regulating GDNF expression, while miR-451 influences drug resistance in renal cell carcinoma by targeting GDNF." (PMID 32102656, 2020).
COVID-19 (5 papers, 2020 to 2026). A disease caused by infection with severe acute respiratory syndrome coronavirus 2. "Both NGF and GDNF levels were significantly lower in COVID-19 patients at admission compared with healthy individuals." (PMID 41714345, 2026). "GDNF also interacts strongly with epidermal growth factor receptor (evidence: affinity capture-MS; green arrow) reported to regulate the severity of COVID-19 in patients." (PMID 39164284, 2024). "For the LC group versus the low-radon group, the top five metabolic pathways were the SARS-CoV-2 and COVID-19 pathway, GDNF signaling, the conjugation of benzoate with glycine, the pirenzepine action pathway, and the amino acid conjugation of benzoic acid." (PMID 39766081, 2024). "In contrast, for the LC group versus the high-radon group, the top five metabolic pathways included amino acid conjugation, the conjugation of carboxylic acids, the SARS-CoV-2 and COVID-19 pathway, GDNF signaling, and the conjugation of benzoate with glycine." (PMID 39766081, 2024). "The precise role of GDNF in COVID-19 related pathologies is unknown but may represent a compensatory immunometabolic adaptation related to changes in energy metabolism in infected AGMs." (PMID 39164284, 2024).
Crohn disease (5 papers, 2011 to 2018). A gastrointestinal disorder characterized by chronic inflammation involving all layers of the intestinal wall, noncaseating granulomas affecting the intestinal wall and regional lymph nodes, and transmural fibrosis. "In Crohn’s disease, for instance GDNF protects the enteric glial cells of the intestinal mucosa against apoptosis, thus preserving its integrity and function." (PMID 29208768, 2018). "This study proposes the existence of an autocrine anti-apoptotic loop in EGC cells which is operative in Crohn's disease and dependent of GDNF." (PMID 22251670, 2012). "But within that, inflammatory stages showed induced up-regulation in GDNF concentrations in inflamed areas, whereas GDNF was down-regulated in non-inflamed tissue of patients with Crohn's disease." (PMID 28152033, 2017). "Whereas these inflammatory states showed induced up-regulation of GDNF concentrations in inflamed areas, GDNF was down-regulated in non-inflamed tissue of patients with Crohńs disease." (PMID 23805210, 2013). "We have identified high level of GDNF expression in mucosal EGC from patients with Crohn's disease, whereas GDNF was not detectable in healthy controls." (PMID 22251670, 2012). "Although the GDNF and GFAP content are increased in Crohn's disease (CD), it is significantly less." (PMID 21235736, 2011).